GABRA2 (gamma-aminobutyric acid type A receptor subunit alpha2)
Description:
Alpha subunit of the heteropentameric ligand-gated chloride channel gated by gamma-aminobutyric acid (GABA), a major inhibitory neurotransmitter in the brain. GABA-gated chloride channels, also named GABA(A) receptors (GABAAR), consist of five subunits arranged around a central pore and contain GABA active binding site(s) located at the alpha and beta subunit interfaces (By similarity). When activated by GABA, GABAARs selectively allow the flow of chloride anions across the cell membrane down their electrochemical gradient. Chloride influx into the postsynaptic neuron following GABAAR opening decreases the neuron ability to generate a new action potential, thereby reducing nerve transmission (By similarity). The alpha-2 subunit exhibits synaptogenic activity together with beta-2 and very little to no activity together with beta-3, the gamma-2 subunit being necessary but not sufficient to induce rapid synaptic contacts formation (By similarity).
Synonyms: DEE78; EIEE78
Tractability: Small molecule: an approved drug acts on it; a structure with a bound ligand is known; a high-quality ligand is known; it belongs to a druggable protein family. Antibody: its Gene Ontology location is reachable by antibodies, with high confidence; UniProt places it where antibodies can reach, with medium confidence; UniProt predicts a signal peptide or a membrane-spanning region; the Human Protein Atlas places it where antibodies can reach. PROTAC: its protein half-life has been measured; a small molecule that binds it is known.
Target class: Ion channel; GABA-A receptor; Ligand-gated ion channel
Safety:
Unwanted effects reported when the protein is acted on. In parentheses: how it was acted on, where the effect was seen, and who reports it.
ataxia (activation, acute dosing; central nervous system, cardiovascular; source: Lynch et al. (2017))
convulsions (inhibition, acute dosing; central nervous system, cardiovascular; source: Lynch et al. (2017))
decreased anxiety (activation, acute dosing; central nervous system, cardiovascular; source: Lynch et al. (2017))
decreased blood pressure (activation, acute dosing; central nervous system, cardiovascular; source: Lynch et al. (2017))
decreased body temperature (activation, acute dosing; central nervous system, cardiovascular; source: Lynch et al. (2017))
decreased cardiac contractility (activation, acute dosing; central nervous system, cardiovascular; source: Lynch et al. (2017))
decreased convulsions (activation, acute dosing; central nervous system, cardiovascular; source: Lynch et al. (2017))
decreased locomotor activity (activation, acute dosing; central nervous system, cardiovascular; source: Lynch et al. (2017))
decreased memory (activation, acute dosing; central nervous system, cardiovascular; source: Lynch et al. (2017))
decreased pain (activation, acute dosing; central nervous system, cardiovascular; source: Lynch et al. (2017))
decreased sleep (inhibition, acute dosing; central nervous system, cardiovascular; source: Lynch et al. (2017))
drug abuse/dependence (activation, acute dosing; central nervous system, cardiovascular; source: Lynch et al. (2017))
increased cardiac output (activation, acute dosing; central nervous system, cardiovascular; source: Lynch et al. (2017))
increased eating (activation, acute dosing; central nervous system, cardiovascular; source: Lynch et al. (2017))
increased respiratory rate (activation, acute dosing; central nervous system, cardiovascular; source: Lynch et al. (2017))
increased sleep (activation, acute dosing; central nervous system, cardiovascular; source: Lynch et al. (2017))
muscle relaxation (activation, acute dosing; central nervous system, cardiovascular; source: Lynch et al. (2017))
cocaine cue-reactivity (source: ClinPGx)
Gene: Protein-coding gene on chromosome 4 (46,243,548 to 46,475,230, reverse strand). Ensembl gene ENSG00000151834.
Subcellular location: Postsynaptic cell membrane; Cell membrane; Cytoplasmic vesicle membrane; Cell projection, dendrite
Subcellular location (Human Protein Atlas): Plasma membrane; Nucleoplasm
Pathways (Reactome):
Neuronal System: GABA receptor activation
Gene Ontology:
Molecular function: benzodiazepine receptor activity; GABA-gated chloride ion channel activity; ligand-gated monoatomic ion channel activity involved in regulation of presynaptic membrane potential; protein binding; transmitter-gated monoatomic ion channel activity involved in regulation of postsynaptic membrane potential; GABA-A receptor activity; extracellular ligand-gated monoatomic ion channel activity; monoatomic ion channel activity; signaling receptor activity; transmembrane signaling receptor activity
Biological process: chloride transmembrane transport; gamma-aminobutyric acid signaling pathway; inhibitory synapse assembly; synaptic transmission, GABAergic; chloride transport; monoatomic ion transmembrane transport; monoatomic ion transport; regulation of postsynaptic membrane potential; regulation of presynaptic membrane potential
Cellular component: GABA-A receptor complex; synaptic vesicle membrane; cytoplasmic vesicle membrane; dendrite membrane; plasma membrane; postsynapse; postsynaptic membrane; axon; dendrite; GABA-ergic synapse; inhibitory synapse; membrane; neuronal cell body; postsynaptic specialization membrane
Genetic constraint (gnomAD): Loss-of-function variants: 7 observed, 26.82 expected, observed/expected ratio (o/e) 0.26, 90% interval 0.15 to 0.49. The upper end of that interval is the gene's LOEUF score, 0.49, which puts it in group 2 of 6, group 1 being the genes least tolerant of losing a copy. Missense variants: 188 observed, 366.86 expected, observed/expected ratio (o/e) 0.51, 90% interval 0.45 to 0.58. Synonymous variants: 121 observed, 126.09 expected, observed/expected ratio (o/e) 0.96, 90% interval 0.83 to 1.12.
Homologues: Orthologues: chimpanzee GABRA2 (100% identical), macaque GABRA2 (99% identical), pig GABRA2 (99% identical), guinea pig GABRA2 (98% identical), dog GABRA2 (98% identical), rabbit GABRA2 (98% identical), mouse Gabra2 (98% identical), rat Gabra2 (98% identical), tropical clawed frog gabra2 (84% identical), zebrafish gabra2a (82% identical). Paralogues in human: GABRA1 (76% identical), GABRA3 (72% identical), GABRA5 (72% identical), GABRA4 (58% identical), GABRA6 (57% identical), GABRG1 (43% identical), GABRG2 (42% identical), GABRG3 (41% identical), GLRA2 (36% identical), GLRA1 (36% identical), GLRA3 (35% identical), GABRE (35% identical), and 33 more.
Diseases named in the same sentence as GABRA2 in open-access papers:
GABRA2 is named in the same sentence as 56 diseases in open-access papers, as found by Europe PMC text mining. Sharing a sentence is not in itself a finding about the gene and the disease. The quoted sentences say what the papers report.
alcohol dependence (24 papers, 2005 to 2024). Physical and psychological dependence on alcohol. "Taken together, there is evidence that GABRA2 genetic polymorphisms and functional consequences contribute to the risk of alcohol dependence and related phenotypes and have detectable but minor effects on DSM-defined AUD." (PMID 36422192, 2022). "Background and Objectives: Variants of GABRA2 have been repeatedly associated with alcohol dependence risk." (PMID 36422192, 2022). "GABRA2 and alcoholism have been linked to individual differences in beta oscillation power (12–28 Hz)." (PMID 34291596, 2021). "In support of Gabra2-Gabrb1 covariance in expression, a GABRA2 risk variant for alcohol dependence leading to reduced expression of GABRA2 positively correlated with expression of GABRB1, GABRG1 and GABRA4 in human iPSCs." (PMID 34677900, 2021). "Alcohol dependence has been found to be linked to SNPs in gamma‐aminobutyric acid‐receptor subunit alpha 2 gene (GABRA2)." (PMID 34291596, 2021). "Genetic variation at the GABRA2 locus has been implicated in epilepsy, affective and psychiatric disorders, alcoholism and drug abuse." (PMID 30984232, 2019). "Several GWAS studies have demonstrated that human GABRA2 genetic variants are associated with alcohol dependence." (PMID 27768696, 2016). "Of note, GABRA1 is a member of the same gene family as GABRA2, which was reported recently to be associated with alcoholism." (PMID 16451705, 2005). "Among these genes, GABRA1 is a member of the same gene family with GABRA2 that was recently reported as alcoholism susceptibility gene." (PMID 16451705, 2005). "Moreover, offspring from families with multiple cases of alcohol dependence have a greater likelihood of developing AUD that is caused by an interaction between allelic variation in GABRA2 and BDNF genes." (PMID 38928583, 2024). "GABRA2 variation has been implicated in alcoholism and drug abuse in human populations." (PMID 34512422, 2021). "In addition, human genetic linkage studies show a strong association of GABRA2 (the gene encoding the α2 subunit) with alcohol dependence." (PMID 25278838, 2014). "In addition, several association studies have implicated GABRA2 in alcohol dependence." (PMID 17373405, 2006). "Even protection from alcohol dependence has been attributed to GABRA1 and GABRA2 polymorphisms in a small study from India, probably due to ethnic stratification effects." (PMID 36422192, 2022). "We investigated global DNA methylation, as well as DNA methylation pattern of 4 CpG sites in the 5′-region of the GABRA2 gene in peripheral leukocyte DNA from 47 alcohol-dependent patients and 41 healthy controls." (PMID 36422192, 2022). "The target of ‘Acebutolol’ is ‘Beta-1 adrenergic receptor’ (ADRB1: ADR), the disease gene of ‘Alcohol Dependence’ is ‘Gammaaminobutyric acid receptor subunit alpha-2’ (GABRA2: GABR)." (PMID 24244318, 2013). "Changes specific to alcoholism were the down-regulation of GABRA2 (FDR p = 0.028) and a trend down-regulation of GABRG1 (FDR p = 0.056)." (PMID 22253714, 2012). "We reported significant linkage and linkage disequilibrium for the beta frequency of the EEG and GABRA2, a GABAA receptor gene on chromosome 4, which we found is also associated with diagnosis of alcohol dependence and related disorders." (PMID 17982586, 2007). "Consistent with functional studies of the GABAA receptor, COGA linkage studies had identified a large DNA region located on chromosome 4, which contains the GABRA2, GABRA4, GABRB1, and GABRG1 genes, as being related to the risk of alcoholism." (PMID 17373405, 2006). "Influences of GABRA2 on characteristics of alcohol dependence may be exerted by mechanisms other than epigenetic alterations related to alcohol intoxication or withdrawal." (PMID 36422192, 2022). "This suggests that hippocampal GABRA2 expression affects beta oscillations and may be linked to the pivotal role hippocampal GABA plays in habit‐forming and reward processing in alcohol dependence." (PMID 34291596, 2021).
alcohol dependence (continued). "The PCR fragment amplified with our GABRA2 primers covers the region between exon 6 and 7, which does not have any common GABRA2 SNPs (single nucleotide polymorphisms) associated with alcohol dependence." (PMID 25278838, 2014). "In addition, a gene encoding one of the receptors for the neurotransmitter γ-aminobutyric acid (GABA) known as GABRA2 seems to have a role in the development of alcohol dependence." (PMID 23134043, 2012). "We found significant linkage and association between brain oscillations and genes involved with inhibitory neural networks (e.g., GABRA2, CHRM2), including frontal networks that are deficient in individuals with alcohol dependence, impulsivity, and related disinhibitory disorders." (PMID 17982586, 2007). "In addition, GABRA6, GABRG1, and GABRG2 polymorphisms (GABAAR α6, γ1 and γ2 subunit) appear to be linked to alcoholism independent of GABRA2." (PMID 27199667, 2016). "Other characteristics of alcohol use disorders, such as average alcohol intake during the last month, withdrawal severity or duration of alcohol dependence, had no influence on GABRA2 methylation patterns." (PMID 36422192, 2022). "The investigators identified several SNPs located in the GABRA2 gene that were associated with alcohol dependence; in the neighboring genes encoding other GABAA receptor components, however, no SNPs related to alcohol dependence were identified." (PMID 17373405, 2006).
Anxiety (17 papers, 2014 to 2025). Intense feelings of nervousness, tension, or panic often arise in response to interpersonal stresses. "Altered expression of Gabrr2, Gabra6 and Gabra2 is implicated in the pathogenesis of anxiety and depression." (PMID 34448534, 2021). "Variations in the GABRA2 gene have been linked to conduct disorder, impulsivity and anxiety, all of which are known to influence drug taking." (PMID 24481569, 2014). "Genetic investigations have further identified conserved risk variants in genes like BDNF and GABRA2, which modulate amygdala reactivity and stress resilience across species, underscoring the evolutionary conservation of anxiety-related neural mechanisms." (PMID 40635883, 2025). "Similarly, data from both rats and mice demonstrated an association between lower baseline Gabra2 expression and a high anxiety phenotype." (PMID 30555510, 2018). "Because βE works via GABA signaling to reduce anxiety, we sought to determine whether sexually dimorphic binge drinking behavior in βE deficient mice is coupled with differences in CNS Gabra2 expression." (PMID 30555510, 2018). "Mice with a mutation in the Gabra2 gene have heightened baseline levels of anxiety." (PMID 30555510, 2018). "Many studies have indicated GABRA2 is involved in anxiety, stress response, and depression, and it is also thought to have a role in neurological disorders such as early-onset epilepsy, early-onset epileptic encephalopathy, and schizophrenia in humans." (PMID 39766878, 2024). "The GABAAα2 subunit (the Gabra2 gene) plays an important role in the regulation of anxiety being modulated by benzodiazepines, barbiturates, and ethanol." (PMID 37926812, 2023). "In the Gabra2-1 animal model, altered clustering of GABAARs containing the α2 subunit led to developmental seizure and mortality, as well as anxiety-like phenotypes." (PMID 31297048, 2019). "The Gabra2–1 mutation demonstrates a striking parallel with the effects of ARHGEF9 mutation in human syndromes, whose symptoms include epilepsy, anxiety, mental retardation, aggressive behavior, sleep–wake cycle disruptions, early mortality, and hyperekplexia." (PMID 30087324, 2018). "Adult Gabra2–1 mice that survive have increased anxiety-like behavior and EEG abnormalities that are responsive to α2-selective benzodiazepines, revealing a novel therapeutic potential for these compounds." (PMID 30087324, 2018). "Surviving Gabra2-1 mice show anxiety and elevations in electroencephalogram δ power, which are ameliorated by treatment with the α2/α3-selective positive modulator, AZD7325." (PMID 30087324, 2018). "Gabra2-1 mice also display anxiety-like behavior, and an enhancement of power in the δ-band using electroencephalogram (EEG) recording, both of which are ameliorated by treatment with the α2/α3-selective GABAAR positive modulator AZD7325." (PMID 30087324, 2018). "The reduced anxiety phenotype together with increased GABRA2 expression observed in the present study supports such an association." (PMID 27536216, 2016). "In contrast, EE mice in the current study show reduced anxiety together with increased GABRA2 expression levels." (PMID 27536216, 2016). "Contradictorily, a study conducted in mice fed a methyl-deficient diet, showed the opposite effects, such that a decrease in the expression of Gabra2 in mouse hippocampus correlated with a decrease in anxiety-like behaviors, although hippocampal and whole-brain studies are difficult to compare." (PMID 35998298, 2023). "Receptors containing the α2 subunit (GABRA2) are abundantly expressed in mouse hippocampus, frontal cortex, amygdala, dorsal and ventral striatum, and hypothalamus—brain regions important for motivation, reward, anxiety, depression, and fear." (PMID 30984232, 2019). "In addition, GABAAR agonist drugs like diazepam that reduce anxiety increase central Gabra2 mRNA expression." (PMID 30555510, 2018).
Anxiety (continued). "Along with previous studies, our results suggest an inverse correlation between Gabra2 expression and anxiety, with subjects that have a lower baseline of Gabra2 expression exhibiting an overly anxious phenotype and with Gabra2 expression increases associated with significant anxiolytic responses." (PMID 30555510, 2018). "Interestingly, ad libitum intake of a normal diet reversed the decreased expression of Gabra2 but also induced an increase in anxiety-like behavior; in addition, persistently reduced hippocampal expression of Gabra3 was observed in the FMCD group." (PMID 25144567, 2014). "Among its many effects, alcohol consumption reduces anxiety via the inhibitory neurotransmitter GABA, most likely acting upon receptors containing the α-2 subunit (Gabra2)." (PMID 30555510, 2018). "Currently, though the alteration of GABAA and 5-HT receptors under strong oxidative stimulation is unclear, our result in some extent suggested that overexpression of GABRA1, GABRA2, HTR1A, HTR1B, and HTR2A may be involved in oxidative stress-induced anxiety." (PMID 33178009, 2020). "While AZD7325 reduced anxiety-like behavior in both Gabra2–1 mice and wildtype controls, we found that the classical benzodiazepine diazepam was not effective at reducing anxiety-like behavior in Gabra2–1 mice." (PMID 30087324, 2018). "For example, in males, EtOH affects the activity of the CeA but not the BNST and Gabra2 expression in the CeA is reduced in high anxiety or alcoholic subjects." (PMID 30555510, 2018).